PLK1 (polo like kinase 1)
Diseases named in the same sentence as PLK1 in open-access papers (continued):
Sharing a sentence is not in itself a finding about the gene and the disease.
Sepsis (8 papers, 2018 to 2025). Sepsis is defined as life-threatening organ dysfunction caused by a dysregulated host response to infection. "PLK1 may be a novel player in the underlying molecular mechanism of sepsis-induced intestinal barrier dysfunction." (PMID 29348559, 2018). "The results indicate that sepsis-induced intestinal barrier dysfunction may be the result of disequilibrium between proliferation and apoptosis in intestinal epithelial cells, which is caused by the down-regulation of PLK1." (PMID 29348559, 2018). "For example, it exacerbates intestinal epithelial injury and barrier dysfunction in sepsis via the miR-1306-5p/PLK1 axis." (PMID 41394397, 2025). "Studies have highlighted the role of PLK1 in regulating inflammatory factors in sepsis and related diseases, offering potential insights for anti-inflammatory strategies in tumor treatment." (PMID 40612941, 2025). "The protective effect of PLK1 on sepsis-induced intestinal barrier dysfunction was shown in CAG-PLK1 CLP mice." (PMID 36581806, 2022). "Here, we report a protective role of polo-like kinase 1 (PLK1) in intestinal barrier integrity during sepsis." (PMID 36581806, 2022). "PLK1 overexpression alleviated sepsis-induced damage to the intestinal epithelium by inhibiting the activation of NF-κB signalling." (PMID 36581806, 2022). "In this study, we showed that PLK1 protects against sepsis-induced intestinal barrier dysfunction by improving the imbalance in mitochondrial fusion and fission and reducing apoptosis in the intestinal epithelium." (PMID 36581806, 2022). "In conclusion, our work demonstrates that PLK1 protects against sepsis-induced intestinal barrier dysfunction via TANK/NF-κB signalling by rescuing mitochondrial dysfunction and inhibiting apoptosis in the intestinal epithelium." (PMID 36581806, 2022). "Here, we examined the role of PLK1 in sepsis-induced intestinal injury by overexpressing or inhibiting PLK1 in vivo." (PMID 36581806, 2022). "Though our previous study found the decreased expression of PLK1 in sepsis, we also examined the level of PLK1 in intestinal epithelium during sepsis." (PMID 36581806, 2022). "To further investigate the role of PLK1 in sepsis‐induced muscle atrophy, we established a sepsis model in vitro using C2C12 cells." (PMID 34514712, 2021). "Sepsis downregulated the expression of PLK1 in muscle cells and subsequently inhibited the activity of the AKT pathway, leading to apoptosis of myofibrils and a reduction in myoblast proliferation and thereby resulted in muscle atrophy." (PMID 34514712, 2021). "Taken together, these results indicate that sepsis induces skeletal muscle atrophy by promoting apoptosis of muscle fibres and inhibiting proliferation of myoblasts via regulation of the PLK1‐AKT pathway." (PMID 34514712, 2021). "Here, the expression of PLK1 was detected in sepsis‐induced atrophic gastrocnemius, and the results showed that PLK1 was reduced in atrophic gastrocnemius." (PMID 34514712, 2021). "Second, we were not able to use PLK1+/+ mice; instead we over-expressed the PLK1 gene in HT29 cells as a means of testing the role of PLK1 in sepsis." (PMID 29348559, 2018). "In this study, we found that PLK1 was down-regulated during sepsis in vivo and vitro, and we propose that the down-regulation of PLK1 disrupts the balance between proliferation and apoptosis of intestinal epithelial cells in sepsis." (PMID 29348559, 2018). "To further examine the relationship between PLK1 and sepsis, we treated HT29 with various doses of LPS and then detected the expression of PLK1." (PMID 29348559, 2018). "In this study, we assessed apoptosis and proliferation in intestinal mucosal cells in sepsis and detected the expression of PLK1." (PMID 29348559, 2018). "In contrast, PLK1 exhibits a protective role in sepsis-induced intestinal barrier dysfunction." (PMID 40612941, 2025). "Additionally, PLK1 has been identified as a key contributor to sepsis-induced myocardial dysfunction (SIMD)." (PMID 40612941, 2025).
Sepsis (continued). "Our findings reveal that the PLK1/TANK/NF-κB axis plays a crucial role in sepsis-induced intestinal barrier dysfunction by regulating mitochondrial dynamics and apoptosis in the intestinal epithelium and might be a potential therapeutic target in the clinic." (PMID 36581806, 2022). "PLK1 is present in proliferative tissues such as the bone marrow, and its overexpression promotes cell proliferation and was shown to partly rescue proliferation inhibition in an in vitro sepsis model." (PMID 35143591, 2022). "Furthermore, we explored the potential mechanism of PLK1 on sepsis-induced intestinal injury in vivo and in vitro." (PMID 36581806, 2022). "PLK1 also targeted the Caspase3‐dependent apoptosis pathway and E3 ubiquitin ligases, which may be another mechanism of sepsis‐induced muscle atrophy." (PMID 34514712, 2021). "Here, we hypothesized that sepsis induces apoptosis and inhibits the proliferation of muscle cells, thus resulting in muscle atrophy, and this process is regulated by PLK1‐AKT signalling." (PMID 34514712, 2021). "In summary, our study demonstrates that sepsis induces skeletal muscle atrophy by promoting apoptosis of myofibres and inhibiting proliferation of myoblasts and that this process is regulated by the PLK1‐AKT pathway." (PMID 34514712, 2021). "To determine whether PLK1 is involved in sepsis-induced apoptosis of intestinal epithelial cells, we examined the expression of PLK1 with immunohistochemistry and western blot." (PMID 29348559, 2018). "The aim of this study is to investigate whether Polo-like kinase 1 (PLK1) ameliorates sepsis-induced intestinal barrier dysfunction in the intestinal epithelium." (PMID 29348559, 2018). "Our previous studies revealed that PLK1 overexpression could rescue lipopolysaccharide (LPS)-induced apoptosis in different types of cells in vitro, but little is known about its role during sepsis in vivo." (PMID 36581806, 2022). "Thus, the PLK1/TANK/NF-κB axis was shown to play a crucial role in sepsis-induced intestinal barrier dysfunction and might be a potential therapeutic target in the clinic." (PMID 36581806, 2022). "For instance, in sepsis-induced acute lung injury (ALI), the activation of the ROS-mediated NLRP3 inflammasome is suppressed through modulation of the PLK1/AMPK/DRP1 signaling axis." (PMID 40612941, 2025). "To explore the mechanisms involved, we focused on the recently identified PLK1/AMPK/DRP1 signaling axis, which has been shown to inhibit ROS-mediated NLRP3 inflammasome activation and attenuate sepsis-induced acute lung injury." (PMID 40918153, 2025). "Mice with PLK1 overexpression (CAG-PLK1 mice) or PLK1 inhibition (BI2536-treated mice) underwent caecal ligation and puncture (CLP) to establish a sepsis model." (PMID 36581806, 2022). "The findings revealed that TAN mitigated sepsis-induced ALI in mice through various pathways, primarily by inhibiting ROS-mediated activation of the NLRP3 inflammasome and modulating the polo-like kinase 1 (PLK1)/AMPK/dynamin-related protein 1(DRP1) signaling pathway." (PMID 38675431, 2024). "Therefore, we hypothesize that PLK1 negatively regulates NF-κB signalling by binding and inhibiting TANK in the intestinal epithelium during sepsis." (PMID 36581806, 2022). "PLK1 also regulates the Caspase3‐dependent apoptosis pathway and the activity of the E3 ubiquitin ligases MURF1 and Atrogin‐1, which may be another mechanism of sepsis‐induced myofibre atrophy." (PMID 34514712, 2021).
clear cell renal cell carcinoma (7 papers, 2019 to 2024). "validated that PLK1 was highly expressed in clear cell renal cell carcinoma (ccRCC) tissues and promoted ccRCC cell proliferation, migration, invasion, and cell cycle." (PMID 36618405, 2022). "We demonstrated that a HIF-2-dependent regulatory pathway drives Plk1 expression in clear cell renal cell carcinoma (ccRCC)." (PMID 33547392, 2021). "Additionally, studies have shown that PLK1 can promote the progression and metastasis of clear cell renal cell carcinoma by upregulating hypoxia-inducible factor 2, which transcriptionally targeting the hypoxia-responsive element of the PLK1 promoter." (PMID 36267972, 2022). "Similarly, CLIC5 expression was found to be lower than that of normal kidney tissues in renal clear cell carcinoma tissues extracted from our research center, while MXD3, NUF2, PABPC1L, and PLK1 were significantly higher in renal clear cell carcinoma tissues than in normal kidney tissues." (PMID 38546385, 2024).
ovarian tumor (7 papers, 2014 to 2025). "In another study, LNPs decorated with anti-EGFR antibodies and loaded with Cas9 mRNA and PLK1 sgRNA were injected intraperitoneally into mice bearing disseminated ovarian tumors." (PMID 39256822, 2024). "The LNPs were efficiently taken up by the ovarian tumors, and gene editing of the PLK1 locus occurred within the tumor cells." (PMID 39256822, 2024). "They found that the LNPs were efficiently taken up by ovarian tumors, which led to gene editing of the PLK1 locus in tumor cells." (PMID 37805495, 2023). "Bora/Aurora A activates Plk1 at mitosis entry and have an essential role in ovarian tumor development." (PMID 34646387, 2021). "The differences of CDC25C (P = 0.000), pCDC25CSer216 (P = 0.001), CDK1 (P = 0.000), CHK1 (P = 0.000), CHK2 (P = 0.000), PLK1 (P = 0.000) and Aurora A (P = 0.000) expression had statistical significances among these ovarian tumor groups." (PMID 32393310, 2020).
pancreatic adenocarcinoma (7 papers, 2015 to 2026). "Overexpression of polo-like kinase 1 (PLK1), a crucial mitotic checkpoint protein for cell cycle progression, is associated with unfavorable prognoses in some cancers (e.g., pancreatic adenocarcinoma)." (PMID 40732979, 2025). "In TCGA data analysis in this study, PLK1 works predominantly as an oncogene in pancreatic adenocarcinoma, and its elevated expression is associated with worse prognosis." (PMID 35773310, 2022). "Mettl3 methylates the 3’-untranslated region of polo-like kinase 1 (PLK1) in pancreatic adenocarcinoma cell lines, and then upregulates PLK1 through IGF2BP2 binding to m6A PLK1." (PMID 41517663, 2026). "Recently, a comprehensive study on pancreatic adenocarcinoma using a database of genes involved in RNA methylation has been conducted, and PLK1 has been extracted as one of the genes involved in RNA methylation." (PMID 35773310, 2022). "In conclusion, METTL3 regulates the cell cycle in pancreatic adenocarcinoma cells through the methylation of the PLK1 3′UTR, and its disruption of homeostasis increases cell death via replication stress and may be a new target for radiosensitization." (PMID 35773310, 2022). "In this study, we suggest a possibility of the mechanism for stabilizing PLK1 expression by the METTL3–IGF2BP2 pathway in pancreatic adenocarcinoma, which may be a new therapeutic target." (PMID 35773310, 2022). "Next, we investigated whether high PLK1 expression is a prognostic factor for pancreatic adenocarcinoma using public databases." (PMID 35773310, 2022). "Therefore, we performed immunohistochemical staining of pancreatic adenocarcinoma specimens from patients subjected to preoperative concurrent chemoradiotherapy (CCRT) to investigate the relationship between PLK1 protein expression level and prognosis." (PMID 35773310, 2022). "It is noted that PLK1 pathway is a potential therapeutic target of pancreatic adenocarcinoma." (PMID 29596435, 2018). "Furthermore, data gained from pancreatic adenocarcinoma patients suggests that dysregulation of PLK1 occurred early in carcinogenesis and overexpression of PLK1 was found in pancreatic intraepithelial neoplasia III lesions." (PMID 26090465, 2015). "Deregulation of PLK1 occurred early in carcinogenesis and over-expression in pancreatic intraepithelial neoplasia III lesions of pancreatic adenocarcinoma patients." (PMID 29596435, 2018).
pancreatic ductal adenocarcinoma (7 papers, 2018 to 2025). An infiltrating adenocarcinoma that arises from the epithelial cells of the pancreas. "Studies have shown that, in pancreatic ductal adenocarcinoma, phosphorylation mediated by Polo-like kinase 1 (Plk1) can inhibit the nuclear translocation of NF-κB, thereby reducing PD-L1 expression." (PMID 41035656, 2025). "Another study demonstrated that inhibiting PLK1 led to the upregulation of PD-L1 expression in pancreatic ductal adenocarcinoma, which enhanced anti-tumor immunity and increased tumor sensitivity to immunotherapy." (PMID 39596658, 2024). "PLK1, a well-known player in pancreatic ductal carcinoma development, is a key regulator of cell division and has been associated with tumor growth and metastasis." (PMID 38250721, 2024). "hsa_circ_0000977 upregulates oncogene PLK1 by sponging miR-874-3p in pancreatic ductal adenocarcinoma." (PMID 30458784, 2018). "In pancreatic ductal adenocarcinoma (PDAC), phosphorylation mediated by Polo-like kinase 1 (Plk1) suppresses NF-κB activity." (PMID 41035656, 2025). "Next, we conducted IHC staining of pancreatic ductal adenocarcinoma (PDAC) tissues using antibodies against ALDOA, ATM and PLK1." (PMID 34565365, 2021).
prostate tumors (7 papers, 2014 to 2025). "Given the fact that the frequency of Ras gene mutations in prostate tumors is low, PLK1-induced activation of CRAF provides mechanistic insights into the aberrant activation of CRAF-MEK1/2-ERK1/2 signaling frequently detected in PCa." (PMID 27003818, 2016). "The first aptamer-siRNA conjugate was a PSMA aptamer conjugated with polo-like kinase 1 (PLK1) siRNA in PSMA-expressing prostate tumors." (PMID 35189921, 2022). "Collectively, this study demonstrates that the oncogenic PLK1 inhibits PHGDH, and subsequently compensatory serine uptake and changes in sphingolipid metabolism ultimately drive the cellular proliferation and prostate tumor growth." (PMID 40475404, 2025). "Expression of SPDEF reduced the tumor burden, decreased the number of Ki67 and PH3-positive cells, and reduced mRNA levels of proliferation-specific genes Cdc25b, Cyclin B1, Cyclin A2, PLK1, CKS1, Aurora B and Topo2 alpha in the prostate tumors." (PMID 25254494, 2014).
rectal cancer (7 papers, 2015 to 2025). A primary or metastatic malignant neoplasm that affects the rectum. "The work of Rodel and colleagues is among the first to highlight the role of PLK-1 as a potential predictive factor, indicating that increased expression is associated with poorer responses of rectal cancer to radiotherapy." (PMID 39857637, 2024). "Our aims were to analyse PLK1 in rectal cancer, and its association with clinicopathological variables, overall survival as well as tumour regression to neoadjuvant treatment." (PMID 26047016, 2015). "Our results suggest that PLK1 is a potentially useful prognostic biomarker in rectal cancer patients." (PMID 26047016, 2015). "Recently, Rodel and colleagues reported polo-like kinase 1 (PLK1) to be a novel predictive biomarker for radiation sensitivity in rectal cancer." (PMID 26047016, 2015). "Further prospective studies validating the clinical utility of PLK1, as demonstrated here, in rectal cancer management is needed to reinforce our findings and translate them into clinical use." (PMID 26047016, 2015). "PLK1 expression was quantified with immunohistochemistry in the centre and periphery (invasive front) of rectal cancers, as well as in the involved regional lymph nodes from 286 patients." (PMID 26047016, 2015). "Hence PLK1 appears to be a promising predictive and prognostic biomarker, and herein we investigate its role in rectal cancer." (PMID 26047016, 2015). "We hypothesise that over-expression of PLK1 correlates with poorer outcomes in rectal cancer." (PMID 26047016, 2015).
Serous Ovarian Cancer (7 papers, 2018 to 2025). "The activity of the combinations of onvansertib, an inhibitor of polo-like kinase 1, with gemcitabine or carboplatin was tested using patient-derived xenografts of high-grade serous ovarian carcinoma resistant to cisplatin (DDP)." (PMID 40565172, 2025). "For instance, anti-EGFR-LNPs loaded with Cas9 mRNA and PLK1 sgRNA enabled ~82% of PLK1 gene editing in human serous ovarian adenocarcinomas Ovcar8 (OV8) cells, which strongly inhibited tumor growth and increased overall survival by ~80% in metastatic OV8-bearing mice." (PMID 38516300, 2023).
small cell lung carcinoma (7 papers, 2020 to 2025). Small cell lung cancer (SCLC) is a highly aggressive malignant neoplasm, accounting for 10-15% of lung cancer cases, characterized byrapid growth, and early metastasis. "Navitoclax has been shown to potentiate the cytotoxicity of BI2536 (a PLK1 inhibitor) in 2D and 3D models of small-cell lung cancer, being able to overcome mitotic slippage and favor apoptosis." (PMID 39859203, 2025). "We systematically examined the efficacy of three different polo-like kinase 1 (PLK1) inhibitors in preclinical models of small cell lung cancers (SCLCs)." (PMID 39941812, 2025).
liposarcoma (6 papers, 2017 to 2025). A usually painless malignant tumor that arises from adipose tissue. "Considering the known tumour-promoting roles of TOP2A, PRC1, and PLK1, inhibiting these proteins by miR-143, therefore, helps inhibit liposarcoma progression." (PMID 39736850, 2025). "Functional assay revealed that miR-143 could repress the expressions of topoisomerase 2-alpha (TOP2A), protein regulator of cytokinesis 1 (PRC1), and polo-like kinase 1 (PLK1) to inhibit liposarcoma cell growth and trigger apoptosis." (PMID 39736850, 2025). "Treatment with a PLK1 inhibitor potently induced G2-M cell cycle arrest and apoptosis in liposarcoma cells, indicating that miR-143 could be a therapeutic target for the reversal of drug resistance." (PMID 28978183, 2017). "Expectedly, YAP1 positivity was not restricted to MLS; however, nuclear expression of YAP1 was significantly more prevalent in MLS compared to other liposarcomas, and YAP1‐positive tumors showed strong expression of the YAP1 downstream targets FOXM1 and PLK1." (PMID 30898787, 2019). "MiR-143 inhibits proliferation, induces apoptosis and cytokinesis of dedifferentiated liposarcoma cells by lowering BCL2, TOP2A, PRC1 and PLK1 expression." (PMID 28036291, 2017). "Restoring miR-143 expression inhibited cytokinesis in dedifferentiated liposarcoma cells, with decreased expression of PRC1 and PLK1." (PMID 28978183, 2017).
metastatic disease (6 papers, 2004 to 2024). "Low PLK1 score was significantly associated with presence of metastatic disease." (PMID 26047016, 2015). "Based on our TMA analysis, we observed an increase in PLK1 expression in primary and metastatic melanoma as compared to benign nevi, with a significant increase in metastatic tumors compared to primary tumors." (PMID 38184733, 2024). "An association was found between TP scores and metastatic status, in that patients with metastatic disease had a low TP PLK1 score in 95% of the cases compared to 72% in the non-metastatic disease group." (PMID 26047016, 2015). "Given this, it would be important to evaluate the potential for PLK1 inhibitors in patients with metastatic disease as a future direction." (PMID 22309939, 2012). "Next, PLK1 expression was measured in HCC from 10 patients with metastatic disease and 10 without (GEO dataset GSE364)." (PMID 37648284, 2023).